LRRC18 (leucine rich repeat containing 18)
Description:
May be involved in the regulation of spermatogenesis and sperm maturation.
Synonyms: UNQ933; MGC34773; UNQ9338; VKGE9338
Tractability: No criterion of Open Targets' tractability assessment is met for any kind of drug.
Gene: Protein-coding gene on chromosome 10 (48,909,480 to 48,939,840, reverse strand). Ensembl gene ENSG00000165383.
Subcellular location: Cytoplasm
Subcellular location (Human Protein Atlas): Cytosol
Gene Ontology:
Molecular function: protein binding
Biological process: intracellular signal transduction
Cellular component: cytoplasm
Genetic constraint (gnomAD): Loss-of-function variants: 13 observed, 13.67 expected, observed/expected ratio (o/e) 0.95, 90% interval 0.62 to 1.51. The upper end of that interval is the gene's LOEUF score, 1.51, which puts it in group 6 of 6, group 1 being the genes least tolerant of losing a copy. Missense variants: 374 observed, 345.23 expected, observed/expected ratio (o/e) 1.08, 90% interval 1 to 1.18. Synonymous variants: 155 observed, 137.87 expected, observed/expected ratio (o/e) 1.12, 90% interval 0.99 to 1.28.
Homologues: Orthologues: chimpanzee LRRC18 (97% identical), macaque LRRC18 (96% identical), dog LRRC18 (84% identical), pig LRRC18 (84% identical), rabbit LRRC18 (83% identical), rat Lrrc18 (82% identical), mouse Lrrc18 (81% identical), guinea pig LRRC18 (79% identical), tropical clawed frog lrrc18 (63% identical), zebrafish lrrc18b (53% identical), zebrafish lrrc18a (47% identical). Paralogues in human: LRRC1 (27% identical), SCRIB (26% identical), LRRC40 (25% identical), SHOC2 (25% identical), LRCH1 (25% identical), LRCH2 (23% identical), LRRC2 (23% identical), LRRIQ4 (23% identical), PHLPP2 (23% identical), LRCH3 (22% identical), LRRC7 (22% identical), PIDD1 (22% identical), and 19 more.
Diseases named in the same sentence as LRRC18 in open-access papers:
LRRC18 is named in the same sentence as 3 diseases in open-access papers, as found by Europe PMC text mining. Sharing a sentence is not in itself a finding about the gene and the disease. The quoted sentences say what the papers report.
coronary artery disease (1 paper, 2022). "LRRC18 was also identified as a critical gene in coronary artery disease diagnosis, and its single-nucleotide polymorphisms are associated with systemic lupus erythematosus." (PMID 35885976, 2022).
neurodevelopmental disorder (1 paper, 2023). A behavioral and cognitive disorder with onset during the developmental period that involves impaired or aberrant development of intellectual, motor, or social functions. "To date, PDPR, LRRC18, and PARP14 have not been associated with neurodevelopmental disorders." (PMID 38025430, 2023).
LRRC18 also shares sentences with these, for which no sentence is quoted: systemic lupus erythematosus (1 paper).